BRCA1 (BRCA1 DNA repair associated)
Diseases named in the same sentence as BRCA1 in open-access papers (continued):
Sharing a sentence is not in itself a finding about the gene and the disease.
Infertility (18 papers, 2011 to 2026). "Female infertility increases the likelihood of the presence of pathogenic variants in BRCA1 or BRCA2 sevenfold; similarly, infertile men are also prone to pathogenic variants in BRCA1 or BRCA2." (PMID 39257928, 2024). "Second, it has been shown that mutations in BRCA1 gene in females are associated with low response to ovarian stimulation, and thus pose a major risk factor for infertility." (PMID 29262604, 2017). "Some studies suggested that BRCA1 or BRCA2 mutations were involved in infertility or POI." (PMID 37325546, 2023). "Primary tubal cancer is rare, often affecting postmenopausal women of unknown etiology, but it often occurs in the context of infertility, impoverishment, chronic tubal infection or on a genetic background (BRCA1/BRCA2 mutation)." (PMID 36055172, 2022). "However, not many previous studies have addressed the relevant issue of a potential interference of independent cancer-related determinants of infertility on the results obtained in BRCA1-mutated women." (PMID 31872386, 2020). "Several authors have noted the association of tubal adenocarcinoma with impoverishment, infertility and chronic or genetic salpingitis, prompting a search for a deleterious BRCA1/2 chromosomal mutation, in our patient this association could not be sought due to lack of means." (PMID 36055172, 2022). "Our observation is the first implication of bi-allelic BRCA1 mutations in isolated ovarian dysfunction or infertility in humans, without clinical signs of FA, and highlights the importance of BRCA1 in ovarian development and function." (PMID 39596525, 2024). "It is reported that women carrying BRCA1 mutations tended to develop infertility or POI due to the accumulation of DNA damage which negatively impacting ovarian reserve." (PMID 38822414, 2024). "This study suggests that co-administration of carboplatin and paclitaxel induces cumulative ovarian damage and infertility but a heterozygote genetic predisposition for DNA damage related to BRCA1 gene function does not increase this risk." (PMID 35105904, 2022). "For example, by understanding the mechanisms utilized by mutations in the BRCA1 and BRCA2 to increase reproductive fitness, we may be able to further our understanding of the reproductive system and potentially discover novel treatments for infertility." (PMID 38952711, 2024). "In conclusion, our observation is the first implication of bi-allelic BRCA1 mutations in isolated ovarian dysfunction or infertility/hypofertility in humans, without clinical signs of FA, highlighting the importance of BRCA1 in ovarian development and function." (PMID 39596525, 2024). "Other risk factors include: increased age, use of high-dose estrogens without progesterone for a long period, uninterrupted ovulation due to infertility, no pregnancies, no use of birth control, and defects in the BRCA1 or BRCA2 genes." (PMID 21827672, 2011). "However, only few women with a pathogenic variant in BRCA1 or BRCA2 experience POI, as variants in BRCA1 and BRCA2 are not a monogenic cause of infertility." (PMID 39257928, 2024).
mesothelioma (18 papers, 2015 to 2025). A usually malignant and aggressive neoplasm of the mesothelium which is often associated with exposure to asbestos. "MiST is an open-label parallel-arm phase 2 trial which explored the efficacy of rucaparib, a PARP inhibitor, in patients with PM with BAP1-deficient or BRCA1-deficient mesothelioma pretreated with chemotherapy." (PMID 40361508, 2025). "Depletion of BAP1 protein induced proteasome-mediated degradation of BRCA1 in mesothelioma cells while loss of BAP1 correlated with BRCA1 loss in mesothelioma patient tumour samples." (PMID 36550359, 2023). "We have previously reported that loss of BRCA1 expression in mesothelioma is a common event, and is associated with resistance to spindle checkpoint activator vinorelbine, a drug with relevance to treatment of mesothelioma." (PMID 30405205, 2018). "We next examined whether the frequent loss of BAP1 in mesothelioma tumours in patients correlates with loss of BRCA1 protein expression." (PMID 36550359, 2023). "However, we found that BAP1 is likely to control BRCA1 expression at least in part at the level of protein stability in mesothelioma cells, as its loss upon BAP1 depletion was blocked by proteasome inhibition." (PMID 36550359, 2023). "Moreover, loss of expression of BAP1 and BRCA1 proteins is strongly correlated in tumour samples taken from mesothelioma patients." (PMID 36550359, 2023). "We had previously reported that BRCA1 contributes to SAC integrity in mesothelioma cells in the presence of the microtubule poison, vinorelbine, through regulating the expression and localization of the SAC components, MAD2L1 and BUBR1, respectively." (PMID 36550359, 2023). "BAP1 and BRCA1 are encoded by tumour suppressor genes that are frequently lost in human cancers, with BAP1 the most commonly mutated gene in mesothelioma." (PMID 36550359, 2023). "It has been recently suggested that BRCA1 haploinsufficiency impairs iron metabolism to promote chrysotile-induced mesothelioma via ferroptosis resistance." (PMID 37880686, 2023). "This suggests that while BAP1 and BRCA1 are both important for normal mitotic progression of mesothelioma cells, they are likely to have at least in part distinct functions." (PMID 36550359, 2023). "We therefore set out to characterise the consequences of BAP1 loss on mitotic progression in mesothelioma cells and discovered that BAP1 loss induces mitotic defects through both BRCA1-dependent and independent mechanisms." (PMID 36550359, 2023). "The aim of this study was to assess the functional relationship between BAP1 and BRCA1 and examine their role in genome stability in mesothelioma cells." (PMID 30405205, 2018). "Hence, BAP1 and BRCA1 are both essential for accurate mitotic progression of mesothelioma cells with the role of BAP1 likely explained in part by its regulation of BRCA1 expression." (PMID 36550359, 2023). "Before setting out to explore how loss of BAP1 might regulate mitotic events in mesothelioma, we wished to examine the interdependence of BAP1 and BRCA1 protein expression in mesothelioma cells by Western blot." (PMID 36550359, 2023). "Our data revealed that depletion of BAP1 leads to loss of BRCA1 protein expression in mesothelioma-derived cell lines but not vice versa." (PMID 36550359, 2023). "We then analysed BAP1 and BRCA1 protein expression in three primary mesothelioma cell lines." (PMID 36550359, 2023). "Notably, a recent study showed that BRCA1 in the mesothelioma leads to the co-depletion of MAD2L1 mRNA and protein." (PMID 37174947, 2023).
mesothelioma (continued). "Using two independent siRNAs, we found that BAP1 depletion led to a significant reduction in BRCA1 protein in the MSTO-211H and NCI-H2452 mesothelioma cell lines." (PMID 36550359, 2023). "We therefore propose that BAP1 inactivation causes mitotic defects through BRCA1-dependent and independent mechanisms revealing novel routes by which mesothelioma cells lacking BAP1 may acquire genome instability and exhibit altered responses to microtubule-targeted agents." (PMID 36550359, 2023). "Taken together, these results suggest that BAP1 contributes to regulation of microtubule length and spindle pole attachment during mitosis in mesothelioma cells in a manner that is independent of BRCA1." (PMID 36550359, 2023). "Rucaparib demonstrated higher efficacy in a phase II trial, when given to patients with BAP1-negative or BRCA1-negative mesothelioma with a disease control rate of 58% at 12 weeks (95% CI 37–77; 15 of 26 patients), and at 24 weeks was 23% (9–44; six of 26 patients)." (PMID 37686585, 2023). "Rucaparib demonstrated only modest antitumor efficacy in patients with mesothelioma, and losses of BAP1 or BRCA1 were not predictive of response to rucaparib." (PMID 40361508, 2025).
Ewing sarcoma (17 papers, 2009 to 2025). A small round cell tumor that lacks morphologic, immunohistochemical, and electron microscopic evidence of neuroectodermal differentiation. "Similar phenomena have been observed in Ewing sarcoma, where BRCA1 remains associated with the transcriptional machinery despite DSBs, and with oncogenic RAS, which induces BRCA1 chromatin dissociation." (PMID 37980390, 2023). "The disruption of HR by EWS-FLI1 supports the categorization of Ewing sarcoma as a “BRCAness” tumor, phenotypically mimicking loss of BRCA1 expression." (PMID 36187937, 2022). "In addition, it has recently been reported that PARP inhibitors are effective for the treatment of BRCA1/2-mutated Ewing sarcoma." (PMID 29784019, 2018). "Ewing sarcoma, due to EWS-FLI1 fusion, also exhibits a phenotype similarity to BRCA1-deficient tumors." (PMID 35327946, 2022). "Ewing’s sarcoma cells exhibit high levels of DNA damage and similarity in phenotype to BRCA1/2 mutant breast cancer, providing a molecular basis for the high sensitivity of Ewing’s sarcoma to PARP1 inhibitors." (PMID 30684955, 2019). "Increased sensitivity to DNA damaging agents in Ewing sarcoma can be explained by defective DNA break repair and down regulation of DNA repair genes BRCA1, GEN1, and ATM." (PMID 27248664, 2016). "Similar analysis as above for Ewing’s sarcoma was also done for MDA-MB-436 BRCA1−/− tumors expressing the imaging reporter." (PMID 25984718, 2015). "Although Ewing sarcoma cells showed robust BRCA1 expression with no known mutations, HR was impaired in Ewing sarcoma." (PMID 35327946, 2022). "In addition to the DNA damage repair defects imparted by EWS-FLI1 itself, germline pathogenic variants in DNA damage repair genes, such as APC, BRCA1, FANCC, and RAD51, have been identified in greater than 10% of patients with Ewing sarcoma." (PMID 36187937, 2022). "The molecule BSJ-01-175 is a novel potent CDK12/13 covalent inhibitor, showing high capacity in reducing RNAPII S2 phosphorylation, expression of BRCA1 and BRCA2 genes, and tumour growth of patient-derived xenograft of TC71 Ewing sarcoma cells." (PMID 39533070, 2025). "For example, in Ewing sarcoma, EWS-FLI1 induces R loops, increases the interaction between RNAPII and BRCA1, and inactivates BRCA133." (PMID 30297739, 2018). "In particular, fusion-positive Ewing sarcoma cells (A673 and TC32) exhibit exquisite sensitivity to THZ531, a CDK12/13 inhibitor, resulting in the downregulation of the homologous recombination (HR) and DNA damage checkpoint genes, including BRCA1, ATR, FANCl, and FANCD2." (PMID 40760094, 2025).
thyroid cancer (17 papers, 2012 to 2026). "Our findings suggest that the five BRCA1 SNPs (rs16940, rs799917, rs1799949, rs1799966, rs8176318) and haplotypes of BRCA1 contribute to the susceptibility of developing thyroid cancer." (PMID 40361383, 2025). "Among the women with a BRCA1 mutation there was only one case of thyroid cancer observed; however, this woman also carried a CHEK2 mutation." (PMID 35205705, 2022). "Five BRCA1/2 mutations were detected in 2 thyroid cancers, 2 kidney cancers, and 1 bone cancer, respectively." (PMID 22382806, 2012). "Although pathogenic variants of BRCA1 may have potentially caused thyroid cancer, it is possible to interpret that thyroid cancer was found in individuals with pathogenic BRCA1 mutation." (PMID 40361383, 2025). "The effect of BRCA1 mutations in thyroid cancer patients is partially understood." (PMID 40361383, 2025). "Although the functional consequences of these polymorphisms are not fully understood, they may affect the ability to repair DSBs and raise the possibility of an association between BRCA1 genetic polymorphisms and thyroid cancer." (PMID 38892180, 2024). "BRCA1 is strongly associated with cell proliferation and may be overexpressed in breast, ovarian, and thyroid cancers." (PMID 38892180, 2024). "We analyzed the relationship between single-nucleotide polymorphisms (SNPs) in BRCA1 and BRCA2 and thyroid cancer and conducted a haplotype analysis of these polymorphisms to study the interactions between genetic polymorphisms." (PMID 40361383, 2025). "A study of a Chinese ethnic population evaluated the association of SNPs in the 3′-UTR double-strand break repair genes RAD51, RAD51B, BRCA1 (rs12516, rs8176318), BRCA2 (rs15869), XRCC4, and XRCC5 with the risk of thyroid cancer in 206 patients with PTC." (PMID 40361383, 2025). "Of the 16 patients that presented first tumors other than HBOC core tumors in the study cohort, none presented PV/LPV, and only one presented a VUS in BRCA1 (c.5348T > C, p.Met1783Thr), with thyroid cancer as first malignancy and BC as the second." (PMID 36329109, 2022). "The association of BRCA1 and BRCA2 mutations with thyroid carcinoma has not been well evaluated." (PMID 40361383, 2025). "BRCA1 and BRCA2 mutations do not increase thyroid cancer incidence." (PMID 34577828, 2021).
acute myeloid leukemia (16 papers, 2006 to 2025). Acute myeloid leukemia (AML) is a group of neoplasms arising from precursor cells committed to the myeloid cell-line differentiation. "BRCA1 mutations have been observed in <0.5% of acute myeloid leukemia (AML) cases (COSMIC, Dec 2018)." (PMID 36551764, 2022). "BRCA1/2 are reported to be downregulated in acute myeloid leukemia (AML) cell lines and primary cells from AML patients." (PMID 33671579, 2021). "Recently, it has been shown that high expression of BRE (Brain and Reproductive organ-Expressed), another member of the BRCA1 complex, denotes a favorable prognosis in acute myeloid leukemia (AML)." (PMID 22706632, 2012). "Acute myeloid leukaemia samples showed heterogeneous BRCA1 mRNA levels, which were lower than those of normal bone marrows (P=0.0001)." (PMID 17047656, 2006). "Additionally, 24.1% (7/29) reported atypical BRCA1/2 or Lynch presentation, including renal cell carcinoma, acute myeloid leukaemia, non-Hodgkin’s lymphoma, and gastrointestinal stromal tumour." (PMID 39843919, 2025). "Additionally, mutations in CHEK2 and BRCA2 have been linked to CLL and MDS, RAD51 in acute myeloid leukemia (AML) and MDS, MLH1 in MDS, and BRCA1 in AML." (PMID 34840720, 2021). "Flow cytometry-based single cell network profiling (SCNP) was used to measure drug-induced activation of DNA damage response (DDR) proteins in cell lines with defined HRR pathway mutations (including ATM-/-, ATM+/-, BRCA1+/-, BRCA2-/-) and in primary acute myeloid leukemia (AML) samples." (PMID 24965603, 2014). "We also summarize recent studies using PARPi to treat acute myeloid leukemia (AML), where the majority of AML tumors harbor wild-type BRCA1/2." (PMID 39175540, 2024). "HDAC1 and HDAC2 have been proven to cooperate in regulating BRCA1 transcript and protein expression in acute myeloid leukemia (AML) cells." (PMID 29239146, 2018).
liver cancer (16 papers, 2014 to 2026). An epithelial or non-epithelial malignant neoplasm that arises from the liver. "A recent study demonstrated that approximately 2% (7/357) of patients with primary liver cancer carried BRCA1/2 germline mutations, most of which (5/7) were intrahepatic cholangiocarcinoma." (PMID 32957395, 2020). "In liver cancer, all pathogenic BRCA1/2 alterations were somatic." (PMID 40420266, 2025). "BRCA1 mutation did not increase the incidence of oesophageal cancer, liver cancer, gallbladder and bile duct cancer or bone cancer." (PMID 34577828, 2021). "In liver cancer, autoantibodies frequency to three TAAs were 25.0% (19/76), 5.3% (4/76) and 0% (0/76), 5.3% (4/76), 0% (0/76) and 0% (0/76) were shown to have autoantibody to PARP1 and BRCA1, PARP1 and BRCA2, or BRCA1 and BRCA2, respectively." (PMID 25865228, 2015). "Although BRCA1 silencing did not affect radiosensitivity in SNU449, we cannot rule out the possibility that the HR pathway may also contribute to the proton sensitivity in liver cancer." (PMID 31194786, 2019).
prostate tumors (16 papers, 2008 to 2024). "We employed 14 patient-derived tumor graft models pancreatic, lung, and prostate tumor graft models harboring HR mutations (BRCA1/2, CHK1/2, ATM/ATR, PALB2, PARP1/2, RAD51, FANCA/B) to compare LP-184’s potency with PARPi olaparib." (PMID 38630886, 2024). "We propose that future studies should explore this RAD18/UBC13/PALB2/RNF168 fork recovery pathway in additional models of BRCA1-deficient cancers, including breast and prostate tumors." (PMID 38943334, 2024). "Breast, ovarian, and prostate tumors carrying BRCA1/2 mutations display sensitivity to PARP inhibitors." (PMID 36350633, 2022). "Several PARP1/2/3 inhibitors (PARPi) have had success in treating ovarian, breast and prostate tumors harboring defects in the homologous recombination (HR) DNA repair pathway, especially BRCA1/2 mutated tumors." (PMID 33005627, 2020). "Focusing on the germline variants identified within genes involved in HR, most variants showing LOH were in agreement with known genotype–phenotype correlation as indicted by the observation of BRCA1/2 variants in breast, ovarian and prostate tumor samples and BAP1 variants in uveal melanoma." (PMID 31263571, 2019). "These drugs have been found to be particularly effective in treating prostate tumors that have defects in the DNA repair genes such as BRCA1 or BRCA2." (PMID 39246954, 2024). "A total of 30 prostate tumors and 10 control samples were assessed for the expression level of BRCA1 mRNA." (PMID 39246954, 2024). "BRCA1 and BRCA2 both are prostate tumor suppressors and their loss is associated with enhanced cell proliferation and overall cancer progression 34,35." (PMID 26311046, 2015). "We find that BRCA1/2 loss-of-function mutations – when present in both alleles or when coupled with LOH – are associated with the same HR deficiency associated mutational signatures as are present in BRCA1/2-mutant ovarian, breast, or prostate tumors." (PMID 38589664, 2024). "The Cancer Genome Atlas (TCGA) analysis of 333 primary prostate tumors revealed BRCA2 and BRCA1 mutation rates that were quite similar to our study (3% and 1%, respectively), while ATM mutations were slightly more frequent than in our study (4% in TCGA vs. 1% in our study)." (PMID 38256334, 2023). "The BRCA1/2 deficient samples in the training set of CHORD primarily consisted of ovarian, breast, and prostate tumors, which could potentially bias CHORD’s predictions if the mutation footprint of HRD is not universal across tissue types." (PMID 33149131, 2020). "Other solid tumor cancers commonly seen in BRCA1/2 carriers are pancreas and prostate tumors." (PMID 32283892, 2020).